PKD2 (polycystin 2, transient receptor potential cation channel)
Diseases named in the same sentence as PKD2 in open-access papers (continued):
Sharing a sentence is not in itself a finding about the gene and the disease.
cardiovascular disease (2 papers, 2020 to 2025). "Our demonstration that endothelial cell PKD2 channels contribute to flow-mediated vasodilation and reduce blood pressure is a step forward in understanding the physiological significance of this protein and its dysfunction in patients with ADPKD and other cardiovascular diseases." (PMID 32364494, 2020).
connective tissue disorder (2 papers, 2016 to 2021). A disease involving the connective tissue. "PKD2 and PKD2 interact to regulate extracellular matrix secretion or assembly, and mutations can cause altered matrix integrity which may lead to connective tissue disorder." (PMID 28509167, 2016).
digestive system cancer (1 paper, 2025). A primary or metastatic malignant neoplasm involving any part of the digestive system. "After comparing the co-expressed genes in these five digestive system cancers, five genes, PKD2, CDH11, OSMR, ITGB1, and BNC2, were further identified as being associated and interacting with ITGAV through the Venn diagram." (PMID 40018050, 2025).
PKD2 also shares sentences with these, for which no sentence is quoted: nephronophthisis (8 papers); genetic renal disease (3); laryngeal squamous cell carcinoma (3); pharyngeal squamous cell carcinoma (3); congenital nephrotic syndrome (2); glaucoma (2); Hyperinsulinemia (2); kidney (2); melanoma (2); nephrolithiasis (2); nephropathies (2); ovarian carcinoma (2); renal fibrosis (2); retinal degeneration (2); urinary tract infection (2); abetalipoproteinemia (1); adenocarcinoma (1); Alagille syndrome (1); Alport syndrome (1); anaemia (1); Arrhythmogenic right ventricular dysplasia (1); atherosclerosis (1); atrioventricular block (1); autosomal dominant inherited disorder (1); autosomal dominant polycystic liver disease (1); Bartter syndrome (1); blood pressure (1); breast tumor (1); cardiac arrhythmia (1); Caroli disease (1).
A further 50 diseases each share a sentence with PKD2 in 1 paper.